PBOV1 (prostate and breast cancer overexpressed 1)
Synonyms: UC28; UROC28; dJ171N11.2
Tractability: No criterion of Open Targets' tractability assessment is met for any kind of drug.
Gene: Protein-coding gene on chromosome 6 (138,215,986 to 138,218,491, reverse strand). Ensembl gene ENSG00000254440.
Subcellular location: Cytoplasm; Nucleus
Subcellular location (Human Protein Atlas): Nucleoplasm; Cytosol
Gene Ontology:
Cellular component: cytosol; nucleoplasm; cytoplasm; nucleus
Genetic constraint (gnomAD): Loss-of-function variants: 1 observed, 0.47 expected, observed/expected ratio (o/e) 2.11. That is too few expected variants to judge how well the gene tolerates losing a copy. Missense variants: 147 observed, 159.28 expected, observed/expected ratio (o/e) 0.92, 90% interval 0.81 to 1.06. Synonymous variants: 46 observed, 58.67 expected, observed/expected ratio (o/e) 0.78, 90% interval 0.62 to 1.
Diseases named in the same sentence as PBOV1 in open-access papers:
PBOV1 is named in the same sentence as 15 diseases in open-access papers, as found by Europe PMC text mining. Sharing a sentence is not in itself a finding about the gene and the disease. The quoted sentences say what the papers report.
hepatocellular carcinoma (4 papers, 2020 to 2025). A malignant tumor that arises from hepatocytes. "High PBOV1 expression level is also a marker of poor prognosis for patients with hepatocellular carcinoma (HCC) and therapeutic target for HCC." (PMID 36553613, 2022).
breast carcinoma (3 papers, 2013 to 2022). "Using publicly available data we found that higher level of PBOV1 expression in breast cancer and glioma samples were significantly associated with a positive disease outcome." (PMID 27437030, 2016). "Nevertheless, a missense SNP in PBOV1 gene that results in I73T substitution was previously found to be associated with an increased risk of breast cancer in Cypriot population." (PMID 23418531, 2013). "Using publicly available microarray datasets, we found that high levels of PBOV1 expression in breast cancer and glioma samples were significantly associated with a positive outcome of the cancer disease." (PMID 23418531, 2013). "Despite the recent de novo origin and the lack of identifiable functional signatures, a missense SNP in the PBOV1 coding sequence has been previously associated with an increased risk of breast cancer." (PMID 23418531, 2013). "PBOV1 rs6927706 polymorphism is linked to the development of breast cancer." (PMID 36553613, 2022). "It has been previously reported that missense SNP in PBOV1 is correlated to an increased risk of breast cancer, and although this suggests that this positive association might be causal, the mechanism behind this association is currently unclear." (PMID 23418531, 2013). "This hypothesis goes in line with a previous report that the missense SNPs in PBOV1 is associated with an increased risk of breast cancer." (PMID 23418531, 2013). "High levels of PBOV1 expression are connected with a favorable clinical outcome for breast cancer and glioma." (PMID 36553613, 2022). "PBOV1 expression levels positively correlate with relapse-free survival in breast cancer patients and with overall longitude of survival in glioma patients." (PMID 27437030, 2016). "First, we used the GOBO online tool to perform a Kaplan-Meier survival analysis with respect to PBOV1 expression levels in a pooled dataset from 6 independent studies that measured gene expression profiles in the clinical samples of breast cancers." (PMID 23418531, 2013). "In our analysis of data from publicly available microarray experiments, we found that PBOV1 gene expression levels positively correlated with relapse-free survival in breast cancer patients and with overall longitude of survival in glioma patients." (PMID 23418531, 2013). "It has been previously shown that PBOV1 expression in breast cancer and prostate cancer cells is positively regulated by estrogen and dihydrotestosterone, respectively." (PMID 23418531, 2013). "Another group reported that PBOV1 transcription in breast cancer cells was positively regulated by estradiol." (PMID 23418531, 2013). "We decided to investigate whether the expression of PBOV1 in breast cancer and other cancer types is correlated with the disease progression and outcome." (PMID 23418531, 2013). "Finally, we report that the expression levels of PBOV1 in breast cancer and glioma clinical samples positively correlate to patient relapse-free survival." (PMID 23418531, 2013). "Although the PBOV1 protein has recently originated de novo and thus has no identifiable structural or functional signatures, a missense SNP (single nucleotide polymorphism) in it has been previously associated with an increased risk of breast cancer." (PMID 27437030, 2016).
glioma (3 papers, 2013 to 2025). A benign or malignant brain and spinal cord tumor that arises from glial cells (astrocytes, oligodendrocytes, ependymal cells). "Using publicly available microarray datasets, the researchers also found that high levels of PBOV1 expression in breast cancer and glioma samples were significantly associated with positive clinical outcomes." (PMID 41289037, 2025). "Here we found that tumor samples from patients with proneural glioma who survived for more than 209 weeks showed significantly higher PBOV1 expression levels when compared to patients that survived 52–209 weeks (one-tailed T-test p = 0.04)." (PMID 23418531, 2013). "We also found that PBOV1 was highly expressed in primary but not in recurrent high-grade gliomas, suggesting the presence of a negative selection against PBOV1-expressing cancer cells." (PMID 23418531, 2013). "Interestingly, PBOV1 expression was observed in primary but not recurrent high-grade gliomas, suggesting a negative selection against PBOV1-expressing cancer cells." (PMID 41289037, 2025). "PBOV1 is also highly expressed in primary but not recurrent high-grade gliomas, suggesting that immunoediting against PBOV1-expressing cancer cells might occur over the course of disease." (PMID 27437030, 2016). "Moreover, samples of primary proneural glioma tumors showed a higher PBOV1 expression than samples of recurrent proneural gliomas (one-tailed T-test p = 0.001), suggesting that there might be a negative selection against cancer cells expressing PBOV1 over the course of cancer somatic evolution." (PMID 23418531, 2013).
ovarian carcinoma (3 papers, 2018 to 2025). A malignant neoplasm originating from the surface ovarian epithelium. "There are papers with western blots that support the PBOV1 protein in prostate and ovarian cancers and RNA support in lymphoma and leukaemia in the Human Protein Atlas." (PMID 40996716, 2025). "There are papers with western blots that support the PBOV1 protein in prostate and ovarian cancers and RNA support in lymphoma and leukemia in the Human Protein Atlas." (PMID 39713347, 2024). "Similarly, PBOV1 has been reported to be overexpressed in breast, prostate, and ovarian cancer tissues, regulating tumor proliferation; however, the function of PBOV1 on immune cells has not been discovered." (PMID 30231487, 2018).
prostate carcinoma (3 papers, 2013 to 2022). A carcinoma that arises from epithelial cells of the prostate gland. "In prostate cancer cell lines, PBOV1 overexpression was found to promote tumor proliferation and cell cycle progression." (PMID 30231487, 2018). "Early reports indicated that PBOV1 was expressed in breast and prostate cancers and that its expression in tumor cells was upregulated by sex hormone treatment." (PMID 23418531, 2013). "PBOV1 shows a strong tumor-specific pattern of expression with a certain affinity towards such hormone-dependent cancers like breast and prostate cancers." (PMID 23418531, 2013). "However, PBOV1 promotes prostate cancer and can be a biomarker for more advanced prostate cancer." (PMID 36553613, 2022). "We also found insignificant correlations of PBOV1 to FOXA1 and androgen receptor genes in GDS1746 prostate cancer dataset." (PMID 23418531, 2013). "The authors expressed the protein in vitro, produced antibodies and showed that PBOV1 protein was present in the blood of prostate cancer patients but not in the healthy controls." (PMID 23418531, 2013).
autoimmune disease (1 paper, 2018). A disorder resulting from loss of function or tissue destruction of an organ or multiple organs, arising from humoral or cellular immune responses of the individual to their own tissue constituents. "However, the role of PBOV1 in autoimmune diseases is still unknown." (PMID 30231487, 2018).
monocytic leukemia (1 paper, 2018). "Knockdown and chromatin immunoprecipitation (ChIP) assays in THP-1 cells (human monocytic leukemia cell line) revealed that NTT is regulated by the monocyte key transcription factor C/EBPβ and that it binds to the promoter of nearby gene PBOV1 via hnRNP-U." (PMID 30231487, 2018).
pancreatic cancer (1 paper, 2013). "We found publicly deposited microarray data that shows that PBOV1 expression in pancreatic cancer xenografts negatively responds to the treatment with HhAntag, one of the emerging anti-cancer Hedgehog inhibitor drugs." (PMID 23418531, 2013).
testis cancer (1 paper, 2013). "Consistent with this, we found that PBOV1 was expressed in multiple hormone-dependent cancer types, including breast, ovary, uterus, prostate and testis cancer." (PMID 23418531, 2013).
cancer (8 papers, 2013 to 2025). A tumor composed of atypical neoplastic, often pleomorphic cells that invade other tissues. "Prostate and breast cancer overexpressed 1 (PBOV1) was first described to be upregulated in certain cancers involving tumor proliferation and is variably associated with patient survival." (PMID 30231487, 2018). "One notable example is PBOV1, a de novo gene linked to cancer progression." (PMID 41289037, 2025). "In particular, in NSCLC, MALAT1 is involved in STAT3, SRSF7, and PBOV1 (prostate and breast cancer overexpressed 1) pathways; MALAT1 affects the levels of miR-124, miR-374b-5p, and miR-28-5p, which in turn, target STAT3, SRSF7, and PBOV1 mRNAs, respectively." (PMID 35630580, 2022). "We studied the expression of PBOV1 gene in a broad range of cancers and normal tissues using PCR on panels of cDNA from various normal tissues and tumor samples." (PMID 23418531, 2013). "Here we found that PBOV1 expression was significantly higher in samples from cancer stage III than from stage II (p = 0.0012)." (PMID 23418531, 2013). "We profiled PBOV1 expression in multiple cancer and normal tissue samples and found that it was expressed in 19 out of 34 tumors of various origins but completely lacked expression in any of the normal adult or fetal human tissues." (PMID 23418531, 2013). "We propose that PBOV1 is a novel tumor suppressor gene which might act by provoking the cytotoxic immune response against cancer cells that express it." (PMID 27437030, 2016). "Furthermore, we analyze publicly available genomic, microarray and ChIP-seq data to shed light on the possible mechanisms behind PBOV1 transcriptional activation and uncover any links between PBOV1 expression and cancer clinical outcome." (PMID 23418531, 2013). "Based on our findings we speculate that PBOV1 gene could function as a tumor antigen and a suppressor of certain types of cancer." (PMID 23418531, 2013). "By analyzing publicly available ChIP-seq data and transcription profile correlations in microarray datasets, we found some evidence that PBOV1 expression in cancers may be positively regulated by C/EBP transcription factors and by Hedgehog signaling pathway." (PMID 23418531, 2013). "We hypothesize that PBOV1 expression in cancer cells may provoke an immune response against the tumor cells in a similar fashion and thus help the organism to fight the cancer." (PMID 23418531, 2013). "The result above suggests that the activation of PBOV1 expression in cancers could be due to the binding of some specific transcription factors to the promoter region." (PMID 23418531, 2013). "We have hypothesized that PBOV1 could function by provoking an immune response against cancer cells that are expressing it, and that this property could facilitate the fixation of the PBOV1 coding sequence in the human evolutionary lineage." (PMID 23418531, 2013). "We identified distinct genes including KLK4, FN1, PBOV1, TPM2, and FLNA which are known to be involved in PCa pathways along with IGF1, TPD52, and SRSF1 that are involved in different cancer pathways." (PMID 37218885, 2023). "Unlike cancer/testis antigens genes PBOV1 is expressed from a GC-poor TATA-containing promoter which is not influenced by DNA methylation and is not active in testis." (PMID 27437030, 2016). "We found that, unlike the cancer/testis antigens that are typically controlled by CpG island-containing promoters, PBOV1 was expressed from a GC-poor TATA-containing promoter which was not influenced by CpG demethylation and was inactive in testis." (PMID 23418531, 2013). "Again, like BLID, PBOV1 appears to be a cancer antigen rather than a standard coding gene." (PMID 39713347, 2024).
tumor (4 papers, 2013 to 2022). "After it was established, we studied experimentally the tumor specificity of its expression using cDNA panels from normal and tumor tissues, and we found the broad range of tumors in which PBOV1 was specifically expressed." (PMID 36553613, 2022). "The interesting feature of this result is that tumor specificity of PBOV1 expression was predicted by us from its evolutionary novelty." (PMID 27437030, 2016). "We studied the expression of PBOV1 using PCR on panels of cDNA from various normal and tumor tissues." (PMID 27437030, 2016). "We further studied the expression of PBOV1 in a panel of cDNA from clinical tumor samples that had been isolated in our laboratory." (PMID 23418531, 2013). "The PCR experiments on cDNA panels and clinical tumor samples showed that PBOV1 was expressed in tumors of 19 distinct tissue origins, out of 34 tested, and at the same time was silent in all normal fetal and adult tissue types tested." (PMID 23418531, 2013). "We verify our early report of PBOV1 tumor-specific expression with a new series of expression profiling experiments that use a different batch of cDNA samples and include comprehensive controls for cDNA quality and genomic DNA contamination." (PMID 23418531, 2013). "PBOV1, a gene of the recent de novo origin specific to humans, has highly tumor-specific expression profile (see discussion above in PBOV1, de novo originated human gene with tumor-specific expression)." (PMID 27437030, 2016). "Based on this data, we hypothesize that PBOV1 protein may act as a tumor suppressor upon its expression in tumors." (PMID 23418531, 2013). "Hence we conclude that PBOV1 can be classified to tumor-specific antigens (TSA), a class of genes postulated a long time ago, but the attempts to identify specific members have been mostly unproductive, with one notable exception being the alpha-fetoprotein." (PMID 23418531, 2013). "Experimental testing of this hypothesis and the dissection of potential mechanisms of PBOV1 tumor-suppressor activity remains a scope for future investigations." (PMID 23418531, 2013). "The mechanism behind the tumor-specific activation of PBOV1 is unclear." (PMID 23418531, 2013). "Next, we studied the expression of PBOV1 in the cDNA panels of tumor samples." (PMID 23418531, 2013). "We hypothesized that PBOV1 protein acts as an immunological tumor suppressor." (PMID 36553613, 2022). "Since PBOV1 coding sequence has recently emerged de novo and since our analysis did not identify any functional features in the protein, it is unlikely that PBOV1 protein could act as a tumor suppressor by specifically interfering with some cellular mechanisms and pathways." (PMID 23418531, 2013). "We have previously found that PBOV1 lacks orthologs in non-primate genomes and is expressed in a wide range of tumor types." (PMID 23418531, 2013). "We previously analyzed the evolutionary history and EST-derived expression profiles of the genes in this list and, interestingly, we found that one gene in this list, PBOV1, lacked orthologs in non-primate genomes and its mRNA/EST sequences had been exclusively derived from tumor sources." (PMID 23418531, 2013).
infection (1 paper, 2014). The state of being infected such as from the introduction of a foreign agent such as serum, vaccine, antigenic substance or organism. "PRRSV and PBoV1 infection was confirmed in 18.2% and 27.3% of suckling pigs, respectively." (PMID 25266874, 2014).
PBOV1 also shares sentences with these, for which no sentence is quoted: leukaemia (2 papers); lymphoma (2); rheumatoid arthritis (2).